APOL1 (apolipoprotein L1)
Diseases named in the same sentence as APOL1 in open-access papers (continued):
Sharing a sentence is not in itself a finding about the gene and the disease.
Obesity (9 papers, 2016 to 2025). Accumulation of substantial excess body fat. "As such, we aimed to leverage a transgenic APOL1 mouse model by subjecting the animals to a high-fat diet (HFD) to cause diet-induced obesity (DIO)." (PMID 41497611, 2025). "The positive correlation of log TG and log BMI and the inverse correlation of log HDL-C with log ApoL1 indicate the association of serum ApoL1 with typical features of dyslipidemia in obesity or metabolic syndrome (Mets)." (PMID 31619724, 2019). "It is possible that differences in LVH are driven by a combination of APOL1 genotype, underlying metabolic status, obesity/BMI, HTN, and some other unrecognized socioeconomic or racial variables." (PMID 27900314, 2016). "LVH was highly associated with HR APOL1 (OR: 6.2, 95%CI: 1.6, 24.9), as was obesity (OR: 4.7, 95%CI: 1.5, 14.4)." (PMID 27900314, 2016). "To test whether APOL1 risk alleles modulate the inflammatory basis of obesity, we also exposed bone marrow derived macrophages from these mice to pro-inflammatory, pro-hypertensive, and dyslipidemic conditions." (PMID 41497611, 2025). "A pro-inflammatory state is a hallmark of obesity, suggesting a possible interplay between APOL1 and obesity through immune perturbation." (PMID 41497611, 2025). "Nevertheless, obesity and increased urinary secretion of urea nitrogen were associated with a lower risk of APOL1-mediated CKD progression but were not robust enough to pass the sensitivity analysis." (PMID 39857298, 2025). "Obesity, cardiometabolic disease, and CKD are often co-morbid: many patients with APOL1-mediated kidney disease may also be at higher risk for obesity and cardiometabolic disease." (PMID 41497611, 2025). "In order to circumvent these concerns and guarantee the development of obesity in a reliable and speedy fashion, we would recommend future researchers to backcross this APOL1 expression system onto C57Bl/6J mice, speficially Lepob/ob or Ay/a obesigenic systems." (PMID 41497611, 2025). "Together with our data, this may point towards a role in APOL1 HR in increasing obesity odds in African American women." (PMID 41497611, 2025). "Unlike for obesity, multiple studies have identified genetic risk factors underlying this disparity, a portion of which is attributed to DNA variants in the gene APOL1 encoding Apolipoprotein A1 (APOL1)." (PMID 41497611, 2025). "Our results showed an excess of obesity among those with HR APOL1." (PMID 27900314, 2016). "Future studies should seek to clarify whether the effect of APOL1 on CKD severity is related to obesity or whether these two outcomes are independently influenced by the HR profile." (PMID 27900314, 2016). "In summary, this study provides limited evidence that APOL1 high-risk genotypes may be involved in the pathogenesis of obesity in female but not male mice." (PMID 41497611, 2025). "To address this gap, we placed transgenic APOL1 G0, G1, and G2 FVB/NJ mice on a high-fat diet and analyzed them for weight gain as well as obesity-related cardiometabolic phenotypes." (PMID 41497611, 2025). "AA children with HR APOL1 genotype and FSGS have increase prevalence of obesity and LVH despite a later age of FSGS onset, while adjusting for socioeconomic status." (PMID 27900314, 2016). "Despite the possibility of APOL1 exacerbating cardiometabolic conditions, no in-vivo experimental studies have been conducted to investigate the direct role of APOL1 in obesity." (PMID 41497611, 2025). "Specifically, serum ApoL1 in Mets was significantly higher than in non-obesity or abdominal obesity without insulin resistance." (PMID 31619724, 2019).
renal carcinoma (9 papers, 2021 to 2025). A carcinoma arising from the epithelium of the renal parenchyma or the renal pelvis. "ORO staining showed that there was an obvious lipid reduction in APOL1 deficient renal cancer cells." (PMID 38263248, 2024). "While high expression levels of all three APOL1 allelic variants, G0 (the wild type allele), G1, and G2 are injurious to normal human cells, renal carcinoma cells (RCC) naturally tolerate inherent high expression levels of APOL1." (PMID 35159001, 2022). "Altogether, deregulation of APOL1 protein may be a hallmark of advanced renal cancer." (PMID 38680858, 2024). "In clear-cell renal cell carcinoma, researchers showed that APOL1 predicts poor prognosis of renal cancer and overexpressed APOL1 promoted tumorigenesis and progression." (PMID 40649778, 2025). "Accordingly, APOL1 G1/G2 expression triggers mitochondrial dysfunction, whereas in renal carcinoma cells that are characterized by significant inflammation, APOL1 KO triggers severe autophagy and mitochondrion dysfunction." (PMID 39768205, 2024). "In support to this conclusion, deletion of APOL1 in renal carcinoma cells, which are characterized by inflammation, results in severe mitochondrial dysfunctions." (PMID 39451256, 2024). "One of our important findings was that APOL1 was highly expressed in primary renal cancer cells and retained lower expression patterns in metastatic cells." (PMID 38680858, 2024). "This is how APOL1 expression is increased to promote renal cancer progression through cell metabolic alterations." (PMID 38680858, 2024). "Further transwell assays suggested that APOL1 knockdown suppressed renal cancer cell migration and invasion." (PMID 38263248, 2024). "We have performed MTS assay showed that APOL1-depleted cells were more sensitive to tunicamycin treatment, compared with controls in renal cancer cell lines 786-O." (PMID 38263248, 2024). "We also found that APOL1 and ER Tracker fluorescence were precisely co-localization in the renal cancer cell lines 786-O and A498." (PMID 38263248, 2024). "In this study, we modulated the expression of APOL1 in various renal cancer cell lines and analyzed their proliferative, migratory, and invasive properties." (PMID 38680858, 2024). "To verify the RNA-seq data and that the depletion of APOL1 affected endoplasmic reticulum homoeostasis in the renal cancer cell lines 786-O and A498, we detected UPR-related gene and obtained the similar results." (PMID 38263248, 2024). "Consistently, in renal carcinoma cells that are characterized by important inflammation, APOL1 KO triggers severe autophagy and mitochondrion dysfunctions." (PMID 39451256, 2024). "RNA-seq analysis identified 1017 upregulated and 722 downregulated mRNAs in the renal cancer cell line 786-O (sh-APOL1 vs. sh-Lacz)." (PMID 38263248, 2024). "In the current work, we presented data demonstrating that APOL1 is involved in regulating renal cancer proliferation, metastasis and lipid storage both in vitro and in vivo." (PMID 38263248, 2024). "One of our important findings is that APOL1 localizes to the ER in renal cancer." (PMID 38263248, 2024). "Our study revealed the intracellular function of APOL1 as a tumor suppressor in renal cancer cell EMT and metastasis through FAK/Akt/GSK3β and NFκB, which may be potentially targeted to control ccRCC metastasis." (PMID 38680858, 2024). "Depletion of APOL1 repressed tumor progression and lipid deposition in renal cancer." (PMID 38263248, 2024). "However, we do recognize that many of the results are based on work performed with renal carcinoma cells and HepG2 cells, which are cancerous transformed cell lines that might deviate biologically from healthy normal cells in respect to APOL1 biology." (PMID 40643530, 2025).
renal carcinoma (continued). "Furthermore, ER Tracker imaging indicated ER expansion in APOL1-depleted renal cancer cells 786-O and A498, and ultrastructural analysis by transmission electron microscopy (TEM) confirmed the presence of irregularly and dilated rough ER, both of which are consistent with ER stress." (PMID 38263248, 2024). "Further analysis showed that there was a positive correlation between APOL1 protein and the quantification of ORO (Oil Red O) in renal cancer cell lines and the HK-2 cell line." (PMID 38263248, 2024). "We also examined the expression of APOL1 mRNA in 40 renal cancer tissues and their corresponding noncancerous tissues form The Union hospital and obtained similar results." (PMID 38263248, 2024). "To further support this conclusion, we examined APOL1 protein expression in 5 renal cancer tissues and their corresponding noncancerous tissues from our laboratory and found APOL1 expression was higher in cancer tissues than in adjacent normal tissues." (PMID 38263248, 2024). "As a result, these miRNAs did not specifically suppress APOL1 expression in renal cancer cells as the effect of miR-30a-3p." (PMID 38680858, 2024). "Previous studies have reported that the AOPL1 is a protective factor for renal carcinoma, but the function of APOL1 in LUAD has not been fully illustrated." (PMID 33816503, 2021).
Sepsis (9 papers, 2021 to 2025). Sepsis is defined as life-threatening organ dysfunction caused by a dysregulated host response to infection. "Further, renal dysfunction was the only sepsis-associated organ dysfunction associated with APOL1 high-risk genotypes." (PMID 37882666, 2023). "Two risk variants in the apolipoprotein L1 gene (APOL1) have been associated with increased susceptibility to sepsis in Black patients." (PMID 37882666, 2023). "Third, we performed analyses that included, excluded, and exclusively focused on patients with pre-existing chronic severe renal disease, allowing us to more completely define the contribution of APOL1 high-risk genotypes to the development of sepsis." (PMID 37882666, 2023). "APOL1 high-risk genotypes were associated with an increased risk of sepsis; however, this increased risk was attributable predominantly to pre-existing severe renal disease." (PMID 37882666, 2023). "In conclusion, in this cohort of Black participants hospitalized with infection, APOL1 high-risk genotypes were associated with an increased risk of sepsis; however, this increased risk was attributable predominantly to pre-existing severe renal disease." (PMID 37882666, 2023). "When we adjusted for pre-existing renal comorbidity, the association between APOL1 high-risk genotypes and sepsis was attenuated, and when we removed patients with pre-existing severe renal disease from the analysis, the significant association was nullified." (PMID 37882666, 2023). "This study extends and refines the findings of the MVP study, showing an association, if modest, between high-risk APOL1 genotypes and the occurrence of sepsis among patients admitted to the hospital with infections." (PMID 37882666, 2023). "Within the primary cohort of patients hospitalized with infections, 565 patients developed sepsis, including 105 (29.1%) with APOL1 high-risk genotypes and 460 (24.5%) with low-risk genotypes." (PMID 37882666, 2023). "The risk of sepsis was significantly increased among patients with the high-risk APOL1 genotypes (OR = 1.29 [95% CI, 1.00–1.67; p=0.047])." (PMID 37882666, 2023). "This is consistent with our observation of APOL1 risk alleles increasing the risk of bacterial pneumonia, as most sepsis is caused by bacterial infections." (PMID 33674766, 2021). "A mouse model with endothelial cell specific expression of APOL1 risk alleles, developed increased endothelial inflammation, vascular leakage, albuminuria and increased sepsis severity." (PMID 35095882, 2021). "In contrast to the increased sepsis risk, some in vitro studies have demonstrated that APOL1 restricts HIV infectivity and protects human keratinocytes from the lethal effect of the Staphylococcus aureus α toxin." (PMID 34513880, 2021). "Since delayed neutrophil apoptosis participates in sepsis, the reduction of apoptotic potential of C‐terminal APOL1 variants provides an explanation for the increase in sepsis linked to G1 or G2 expression." (PMID 32530132, 2021). "This retrospective cohort study found that APOL1 high-risk genotypes were significantly associated with an increased risk of sepsis in patients hospitalized with infections; however, this association was explained predominantly by the presence of pre-existing severe renal disease." (PMID 37882666, 2023). "Additionally, in the restricted PheWAS of all Black participants in BioVU (a design parallel to that of the MVP study), we found that APOL1 high-risk genotypes were significantly associated with all prespecified sepsis-related phenotypes." (PMID 37882666, 2023). "Further, it is important to assess whether other organ system dysfunctions typical of sepsis (i.e., hepatic, respiratory, circulatory, and hematologic dysfunction) are associated with APOL1 to appropriately define the causal pathway between APOL1 and sepsis." (PMID 37882666, 2023).
Sepsis (continued). "Given the substantive risks and costs associated with sepsis, as well as the reported association between sepsis and the presence of two APOL1 risk alleles, it is critical to better understand whether APOL1 has a direct association with sepsis." (PMID 37882666, 2023). "First, whether APOL1 high-risk genotypes are associated with the risk of sepsis for patients hospitalized with an infection, particularly independent of the association between the genotypes and severe renal disease." (PMID 37882666, 2023). "Renal dysfunction was the only sepsis-associated organ dysfunction significantly associated with APOL1 high-risk genotypes, and this risk was attenuated by adjustment for pre-existing severe renal comorbidity and nullified by the exclusion of patients with pre-existing severe renal disease." (PMID 37882666, 2023). "However, in an expansion of the original approach, the associations between APOL1 and sepsis-related phenotypes were nullified after we excluded individuals with pre-existing severe renal disease (n=2166) and reran the analyses (n=12, 547)." (PMID 37882666, 2023). "We assessed whether carriage of APOL1 high-risk genotypes was associated with the risk of sepsis and sepsis-related phenotypes in patients hospitalized with infections." (PMID 37882666, 2023). "However, the association between APOL1 high-risk genotypes and sepsis is driven largely by the presence of pre-existing severe renal disease—a potent risk factor for infection, sepsis, and infection-related mortality." (PMID 37882666, 2023). "Furthermore, an excellent research proved that APOL1 risk variants, which are specifically present in individuals of African ancestry, contribute to the exacerbated sepsis." (PMID 36465642, 2022). "Finally, significant association was also noted between expression of the APOL1 variants and sepsis." (PMID 32530132, 2021). "Further, cGAS/STING seem to play a key role in the increased endothelial dysfunction mediated by APOL1 risk variants and might contribute to explain the increased sepsis incidence and severity among patients of African ancestry." (PMID 35095882, 2021). "However, it remains unclear whether APOL1 high-risk genotypes are associated with occurrence of either sepsis or sepsis-related phenotypes in patients hospitalized with infections, independent of their association with pre-existing severe renal disease." (PMID 37882666, 2023). "Second, among patients carrying APOL1 high-risk genotypes, whether the risk of organ dysfunction that defines the presence of sepsis is limited to renal dysfunction or if it affects other typical organ system dysfunction components of sepsis." (PMID 37882666, 2023). "Recent work in the Million Veteran Program (MVP) found that variants in the apolipoprotein L1 gene (APOL1), common in people of African ancestry, are associated with sepsis incidence and severity." (PMID 37882666, 2023). "More specifically, since APOL1 is associated with renal disease and existing renal disease is associated with worse sepsis outcomes (including increased kidney injury), the relationship between APOL1 and sepsis external to existing renal disease remains unclear." (PMID 37882666, 2023). "The objective of this study was to better understand the relationship between APOL1 and sepsis, focusing on two critical points." (PMID 37882666, 2023). "It is therefore possible that the elevated chance of sepsis is not directly linked to these variations of APOL1, but rather is the result of patients already having reduced kidney function." (PMID 37882666, 2023). "This determination of association could help guide the viability of implementing treatment options for sepsis using therapies that target APOL1." (PMID 37882666, 2023). "APOL1 received increasing attention because of its important role in the pathophysiology of sepsis." (PMID 34240756, 2021).
Sepsis (continued). "Previous reports suggest a pathogenic role for APOL1 expressed in endothelial cells in sepsis or circulating immune cells, which this model could not investigate." (PMID 41043427, 2025). "APOL1 high-risk genotypes were significantly associated with the renal dysfunction component of the Sepsis-3 criteria (OR = 1.64 [95% CI, 1.21–2.22; p=0.001]), but not with other sepsis-related organ dysfunction or short-term mortality." (PMID 37882666, 2023). "The lack of association independent of pre-existing severe renal disease suggests that APOL1 high-risk genotypes are not acutely causal of sepsis beyond their association with renal disease and impaired renal function (which, in turn, increases susceptibility to sepsis)." (PMID 37882666, 2023). "However, the association between sepsis and APOL1 high-risk genotypes was not significant after adjustment for pre-existing severe renal disease (OR = 1.14 [95% CI: 0.88–1.48; p=0.33]), nor after exclusion of those patients (n=458) with severe renal disease (OR = 0.99 [95% CI, 0.70–1.39; p=0.95])." (PMID 37882666, 2023). "The involvement of APOL1 in sepsis could be related to the observed correlation between the expression levels of APOL1, but not APOL3, and apoptosis of neutrophils in critically ill patients." (PMID 32530132, 2021).
type 2 diabetes (9 papers, 2011 to 2025). "Literature data suggest that apoL1 is associated with type 2 diabetes mellitus (T2DM), and related to impaired HDL metabolism in insulin resistant states." (PMID 41268158, 2025). "RREB1 polymorphisms have been shown to interact with APOL1, and are implicated in fat distribution and fasting glucose, a potential explanation for the association with type 2 diabetes." (PMID 38812969, 2024). "This is in line with recent studies reporting an association between APOL1 levels in serum and increased risk of type 2 diabetes and the metabolic syndrome." (PMID 37924378, 2024). "Future studies assessing the impact of exogenous APOL1 on beta cells could contribute to the understanding of the role of elevated APOL1 levels in serum, which are associated with type 2 diabetes risk." (PMID 37924378, 2024). "The increase in APOL1 was confirmed by immunostaining in a pancreas section of another donor with type 2 diabetes." (PMID 37924378, 2024).
hepatocellular carcinoma (8 papers, 2017 to 2025). A malignant tumor that arises from hepatocytes. "Other studies have shown that Sp1, IRF1 and IRF2 can bind to the APOL1 promoter in hepatoma cells, and IRF1, IRF2 and STAT2 to the APOL1 promoter in podocytes and endothelial cells." (PMID 37924378, 2024). "APOL1 was observed to be a critical enzyme in lipid functioning and metabolic processes and was found to be aberrantly highly expressed in hepatocellular carcinoma, small-cell lung cancer, and bladder cancer." (PMID 37588985, 2023). "APOL1, as an apolipoprotein, plays a protective role in hepatocellular carcinoma and renal cells carcinoma by mediating tumor cells death." (PMID 33335850, 2020). "Additionally, in hepatoma, ApoL1 expression can be activated by a high level of interferon regulatory factor (IRF) 1, IRF2 and Sp1, all of which are transcription factors that can bind the ApoL1 promoter region." (PMID 36506554, 2022).